IGF1 (insulin like growth factor 1)
Diseases named in the same sentence as IGF1 in open-access papers (continued):
Sharing a sentence is not in itself a finding about the gene and the disease.
autism (continued). "Based on these findings, the reduction in serum IGF-1 levels in early childhood may be associated with the development of ASD, but the mechanism of the association between decreased IGF-1 levels and increased HC, weight, and height in infants with autism has not yet been elucidated." (PMID 38066466, 2023). "In this study, we found a significant positive correlation between Childhood Autism Rating Scale (CARS) scores and IGF-1 immunoreactivity." (PMID 35962006, 2022). "There was a significant positive correlation between Childhood Autism Rating Scale (CARS) scores and IGF-1 immunoreactive levels (Spearman’s correlation rs = 0.486, p = 0.022, n = 22)." (PMID 35962006, 2022). "The present clinical study adds significant preliminary evidence for the use of IGF-1 in the treatment of RTT and other disorders of the autism spectrum." (PMID 26925263, 2016). "BDNF and IGF-1 measures from many of the subjects with autism were previously published as part of an analysis of non-invasive brain stimulation effectiveness in these patients." (PMID 35962006, 2022). "Reduced excretion might be due to increased binding of IGF-1 by the IGF-1 binding protein, insulin-like growth factor binding protein 3 (IGFBP-3) that is increased in blood from autism patients." (PMID 35962006, 2022). "Despite the promise of IGF-1 treatment for autism, CNS IGF-1 levels do not differ between subjects with autism and controls." (PMID 35962006, 2022). "We found that CSF IGF-1 concentrations were low in autism, but only at an early age and not in older children." (PMID 28954393, 2017). "In 25 young children with a diagnosis of autism, it was subsequently shown that IGF-1 levels were significantly reduced, and in those with a diagnosis of autism, Cerebrospinal Fluid (CSF) IGF-1 was correlated with head size." (PMID 27746717, 2016). "Although IGF-1 may be a beneficial treatment for ASD, there appears to be no alteration in IGF-1 levels in autism CNS tissue or fluids compared to controls." (PMID 35962006, 2022). "Finally, HSBP1 and IGF1R were found differentially expressed in autism and, directly or indirectly, modulated by microbiota; namely, HSBP1 is down-regulated after antibiotic administration, and IGF-1 level is affected by gut microbiota composition." (PMID 35405953, 2022). "Recent studies in cells derived from patients with autism and in a clinical case with RTT treated with two cycles of IGF1 suggested that prolonged treatment with IGF1 may not be ideal to produce positive benefits, at least as measured in terms of severity scores and clinical evaluation." (PMID 32756423, 2020).
leukemia (32 papers, 2005 to 2025). A malignant (clonal) hematologic disorder, involving hematopoietic stem cells and characterized by the presence of primitive or atypical myeloid or lymphoid cells in the bone marrow and the blood. "IGF1 is produced in the liver as a growth factor but interestingly, we have found it is also expressed by leukemia-associated myeloid cells, and IGF1R signaling is critical for T-ALL initiation and growth." (PMID 37805579, 2023). "Our results underline the role of microenvironment in concert with the IGF-1 pathway in conferring drug resistance to leukemia cells." (PMID 25095896, 2014). "Larger infants may be at an increased leukemia risk due to increased fetal insulin like growth factor 1 (IGF-1) exposure which has been shown to be positively correlated with birth weight and is a known mitogen for hematopoietic cells." (PMID 18298855, 2008). "Distorted IGF-1/IGF-1R signaling has been linked to the development of aggressive and/or refractory leukemia." (PMID 38159164, 2024). "Leukemia-associated myeloid cells, which directly support survival of mouse T-ALL cells in vitro, produce IGF1." (PMID 39482533, 2024). "Multiple levels of the signaling pathways of insulin and IGF-1 are of capital importance in the pathogenesis of leukemia." (PMID 38159164, 2024). "In a former study on the cognitive effects of GH treatment in adult survivors of childhood leukaemia, the increase in IGF-1 during the first treatment year was accompanied by a decrease in short-term memory performance." (PMID 29980224, 2018). "The addition of IGF-1, which was found in our previous research to reinforce NK cell cytotoxicity, can further strengthen NK cell anti-leukemia activity." (PMID 28915651, 2017). "IGF-1 induces human leukemia cell proliferation and increased DNA replication of liver cell tumor in rat." (PMID 27835910, 2016). "In fact, in a transplantable and spontaneous leukemia mouse model, CR has been shown to reduce serum IGF-1 level and decrease leukemia cell proliferation." (PMID 22934068, 2012). "These authors suggest that IGF-1 could be an important indicator of bone mineralization disorders in children after the completion of leukemia treatment." (PMID 40364018, 2025). "Later on, the same group revealed that T-ALL generated from fetal liver (FL) and adult BM have a dramatic difference in their T-LIC activity, i.e., that FL-derived leukemia with robust NOTCH1-driven autocrine IGF1 signaling exhibits 2-log lower T-LIC activity compared to BM-derived leukemia." (PMID 36428753, 2022). "Interestingly, the anti-proliferative effect of CR on leukemia cells was annulled by restoration of serum IGF-1 concentration." (PMID 22934068, 2012). "IGFBP-2 was identified as the major regulatory carrier in childhood leukemia and exhibited an inverse correlation with IGF-1 levels, suggesting that activation of IGF-1R signaling may confer ALL cells a survival advantage and influence induction of apoptosis." (PMID 20863384, 2010). "Further, co-culture of leukaemia cells with bone marrow-derived stromal cells altered the expression of ABC transporters MDR1, multidrug resistance associated protein 1 (MRP1), MRP2, MRP3 and BRCP in myeloid leukaemia cells in an insulin-like growth factor 1 (IGF1) signalling dependent manner." (PMID 36614005, 2022). "Despite the important role of the IGF1R pathway in myeloid-mediated T-ALL support, exogenous IGF1 is insufficient to sustain T-ALL cell survival in vitro, indicating a role for additional myeloid-derived signals in supporting leukemia cell survival." (PMID 39482533, 2024).
leukemia (continued). "miR-494-3p was mainly paired with immune genes (CD3G, CXCL13, CXCR5, KLRC4), some of which had been annotated as oncogenes in leukemia including IGF1 (DRG; pan-cancer), IKZF3 (driver; leukemia), NABP1 (oncogene; leukemia), and PDGFRA (oncogene; pan-cancer)." (PMID 32605588, 2020). "Besides NFκB, the pro-survival pathways via AKT/mTOR and insulin-like growth factor 1 (IGF-1) have also been described to confer BTZ resistance and may affect the interaction of leukemia cells with (stromal) cells in their micro-environment." (PMID 29071527, 2017). "However, IGF1 is not sufficient to sustain T-ALL in vitro, implicating additional myeloid-mediated signals in leukemia progression." (PMID 37805579, 2023).
Cerebral ischemia (31 papers, 2010 to 2025). Restriction of arterial blood supply to the brain associated with insufficient oxygenation to support the metabolic requirements of the tissue. "It should be noted that intranasally administered IGF-1 has been used for the correction of damage caused by cerebral ischemia–reperfusion for 20 years." (PMID 36834685, 2023). "Activation of hypoxia-inducible factor (HIF)-1α might also be part of the mechanism underlying IGF-1 promoted cell survival after cerebral ischemia." (PMID 25671079, 2014). "IGF-1, produced by microglia, astrocytes, and neurons, likely contributes to neuroprotection by modulating glutamate excitotoxicity in cerebral ischemia models, promoting functional outcomes." (PMID 39624169, 2024). "We identified Zfp580 as a novel factor that differentially modulates paracrine and endocrine Igf1 and Igfbp3 responses after cerebral ischemia." (PMID 35557964, 2022). "After focal cerebral ischemia injury, IGF1 plays an important role in promoting the proliferation of neural progenitor cells and its protein expression increased in the activated astrocytes." (PMID 35153756, 2021). "Insulin-like growth factor-1 (IGF-1) has neuroprotective properties, including protection against global neuronal loss and ameliorating hippocampal damage following cerebral ischemia." (PMID 33233734, 2020). "Mechanistically, the better recovery of skeletal muscle mass in MCAO mice receiving PINTA745 cannot be explained by a specific regulation of IGF-1-Akt-mTOR pathway and autophagy-lysosome system 15 days after cerebral ischemia." (PMID 29070788, 2017). "Recently, multiple growth factors, such as insulin-like growth factor-1 (IGF-1), have been reported to provide beneficial effects on functional recovery in cerebral ischemia." (PMID 24945308, 2014). "Taken together, our results suggest that the IGF-1/Akt pathway contributes to the promotion and survival of neural cells in cerebral ischemia." (PMID 24945308, 2014). "In order to investigate the effected factors of exercise-induced improvement after cerebral ischemia, the expression of IGF-1/AKt pathway were further detected in the present study." (PMID 24945308, 2014). "All these mechanisms, although to varying degrees, are involved in the neuroprotective and anti-inflammatory effects of INI and intranasally administered IGF-1, providing their restorative effect on cognitive, vestibulomotor, and somatosensory functions impaired in cerebral ischemia and TBI." (PMID 36834685, 2023). "While in response to excitotoxic injury, the production of IGF-1 by cultured astrocytes and neurons is increased, consistent with the report that after brain ischemia IGF-1 levels are actually higher due to increased synthesis and accumulation in microglia, vessels and astrocytes." (PMID 31338023, 2019). "Interestingly, we demonstrated significant decreases in the level of IGF-1 on day 7 after cerebral ischemia, when the phosphorylation state of GSK-3β was at its maximum." (PMID 27866373, 2017). "EA administered 15 min after occlusion of MCA enhanced the expression of insulin-like growth factor-1, which might be an important mechanism of neuroprotective effects of EA against cerebral ischemia in monkey." (PMID 23418594, 2013). "Various myokines (e.g., Insulin-Like Growth Factor 1, Irisin) have recently shown their ability to protects against neuronal injury in cerebral ischemia models, suggesting that these substances may influence the degree of neuronal damage in part via inhibiting inflammatory signaling pathways." (PMID 33260365, 2020). "And M2 macrophages enhance neurogenesis and angiogenesis by secreting various neurotrophic factors such as IGF-1, BDNF and VEGF, and promote the recovery of neurological function after cerebral ischemia/reperfusion injury in rats." (PMID 37032832, 2023).
Cerebral ischemia (continued). "Although neurogenesis is coordinately regulated by several factors, our findings imply that an IGF-1- and/or BDNF-independent PI3-K/Akt/GSK-3β pathway was enhanced by cerebral ischemia." (PMID 27866373, 2017). "Other beneficial effects of FGF2 and IGF-1 involved in the subacute administration of zinc might be the stimulation of neuron survival and neurogenesis in the subventricular zone and the subgranular zone of dentate gyrus, since these events are triggered in adult rats following cerebral ischemia." (PMID 26355725, 2015). "According to these recommendations, the current studies of INI and intranasally administered IGF-1 in cerebral ischemia are not without drawbacks and limitations." (PMID 36834685, 2023). "Exercise enhanced IGF-I, and IGF-1 signaling in the ischemic brain can reduce brain ischemia." (PMID 29149058, 2017). "In addition, as the protein levels of insulin-like growth factor-1 (IGF-1) and brain-derived neurotrophic factor (BDNF) were decreased, they might not have been essential for activation of the PI3-K/Akt/GSK-3β pathway after severe cerebral ischemia." (PMID 27866373, 2017). "Furthermore, IGF-1 and BDNF might not be essential for activation of this pathway after severe cerebral ischemia." (PMID 27866373, 2017).
polycystic ovary syndrome (31 papers, 2013 to 2025). A disorder that manifests as multiple cysts on the ovaries. "Due to its similarity with IGF1, in terms of physiological mechanism, we expected that GH would increase follicular recruitment by inducing a pseudo polycystic ovary status, following the increase in local follicular testosterone levels." (PMID 36292058, 2022). "NEAT1 interference-mediated effect induces proliferation and represses apoptosis of ovarian granulosa cells in polycystic ovary syndrome via the microRNA-381/IGF1 axis." (PMID 36523600, 2022). "Third, LH promotes ovarian secretion of IGF-1 which can further promote LH binding and androgen synthesis in theca cell, and finally contributes to the formation of polycystic ovaries in PCOS patients." (PMID 34122341, 2021). "In the remaining patients, gonadal dysfunction could only be attributed to perturbation of the GH/IGF-1 axis and two had polycystic ovary syndrome phenotype, which resolved with normalization of GH and IGF-1 levels." (PMID 36721176, 2023). "Furthermore, HSP 10 was highly expressed in theca cells, and the IGF-1/TGF-β pathway was activated, which caused hyperandrogenemia, and inhibited both follicle maturation and ovulation." (PMID 32471519, 2020). "Furthermore, there are differences between normal and polycystic ovaries in growth responsiveness to IGF1 of follicles during culture of cortical tissue which suggest that PCOS follicles have been exposed to enhanced action of IGFs in vivo." (PMID 30147675, 2018). "Research indicates that the GH/IGF-1 axis plays a significant role in the pathophysiology of polycystic ovary syndrome (PCOS), although clinical study data in PCOS patients remain controversial." (PMID 40270715, 2025). "In polycystic ovarian syndrome (PCOS), where epigenomic instability affects Fshr, Cyp19a1, Esr1, and Igf1, PFASs intensify transcriptional repression through DNMT3A-mediated CpG hypermethylation and global hypoacetylation of H3K9 and H4K16." (PMID 40724853, 2025). "Another study focusing on polycystic ovarian syndrome (PCOS) patients as a target for GH treatment found favorable responses in terms of serum and follicular IGF-1 concentrations." (PMID 31297089, 2019). "Moreover, in polycystic ovarian syndrome of rat, lncRNA-HOTAIR increases the expression of IGF1, which ultimately aggravates endocrinopathy and granulosa cell apoptosis." (PMID 39210795, 2025).
anorexia nervosa (30 papers, 2012 to 2025). A disorder most often seen in adolescent females characterized by a refusal to maintain a minimally normal body weight, an intense fear of gaining weight, a disturbance in body image, and, in postmenarcheal females, the development of amenorrhea. "The hypercortisolemia seen in anorexia nervosa stimulates osteoclasts, causes further dysregulation of the growth hormone-IGF1 axis, and impairs renal and gastrointestinal absorption of calcium, further yielding alterations in bone metabolism." (PMID 35851069, 2022). "Anorexia nervosa is associated with reductions in insulin-like growth factor 1 (IGF1) and growth hormone, which are bone anabolic and facilitate periosteal bone apposition." (PMID 35851069, 2022). "Anorexia nervosa is a state of acquired growth hormone (GH) resistance caused by chronic lack of nutrition leading to an increased GH secretion but decreased systemic insulin-like growth factor 1 (IGF1)." (PMID 38310558, 2024). "Contrary to the bone mineral density loss observed in post-menopausal women, bone loss in anorexia nervosa seems to be driven by a multifactorial process beyond just low estrogen, including hypercortisolemia, and reduced levels of androgens, leptin and insulin-like growth factor 1 (IGF-1)." (PMID 25874112, 2015). "Research has shown that the GH-IGF-1 axis, a major endocrine regulatory mechanism in anorexia nervosa, has IGF-1 levels that are proportional to leptin levels." (PMID 40161302, 2025). "Similar to IGF-1 levels, a reduction in thyroid hormones is also known to occur in states of chronic starvation, including anorexia nervosa, with reversal on refeeding." (PMID 37386483, 2023). "High GH with low IGF-1 can be observed in states of GH resistance such as systemic inflammation, chronic liver disease, cirrhosis, and anorexia nervosa." (PMID 33803429, 2021). "Inversely, a decrease in free IGF1 levels occurs in situations of energy restriction, such as short-term fasting and anorexia nervosa." (PMID 34975768, 2021). "Anorexia nervosa (AN) is characterized by a nutritionally acquired growth hormone (GH) resistance leading to low concentrations of insulin-like growth factor-1 (IGF-1), which is another essential determinant of reduced bone mineral density." (PMID 34207744, 2021). "Indeed, nutritional parameters such as free T3 and IGF1 reached similar normalized levels in both studied anorexia nervosa groups." (PMID 37773179, 2023). "Body weight recovery could be facilitated by treatment with a potent analog of the anabolic hormone IGF1, which is invariably reduced in dietary restrictions including anorexia nervosa." (PMID 27716401, 2016). "Mimicking what is observed in anorexia nervosa patients, and despite a food intake close to that of control mice, separation-based anorexia mice displayed marked alterations in body weight, fat mass, lean mass, bone mass acquisition, reproductive function, GH/IGF-1 axis, and leptinemia." (PMID 25090643, 2014). "Increased GH secretion has also been reported in female athletes compared with non-athletes, and in patients with anorexia nervosa with systemic low IGF-1 levels, indicating a hepatic GH resistance." (PMID 31417414, 2019). "Similarly, treatment with recombinant human IGF-1 has beneficial effects on bone mineral density in adult women with anorexia nervosa but not adolescent girls." (PMID 35874115, 2022). "Therefore, further suppression of IGF-1—a bone anabolic hormone—in anorexia nervosa by oral estrogen may result in the lack of benefit with respect to bone mineral density observed in prospective studies of oral estrogen treatment." (PMID 35874115, 2022). "While there exits one randomized controlled trial of 60 women with anorexia nervosa, that did show a statistically significant increase in bone density following treatment with oral contraceptive pills when coupled with recombinant human IGF-1, further compelling data on this effect are lacking." (PMID 25874112, 2015).
anorexia nervosa (continued). "In addition no clinical role has yet been adopted for IGF-1 in patients with anorexia nervosa." (PMID 25874112, 2015).